MUC4 (mucin 4, cell surface associated)
Diseases named in the same sentence as MUC4 in open-access papers (continued):
Sharing a sentence is not in itself a finding about the gene and the disease.
tumor (continued). "We and other researchers have reported that MUC4 is involved in various biological properties of PC cells, including growth, apoptosis, invasion, tumour angiogenesis and drug resistance." (PMID 27287498, 2016). "Knockdown of MUC4 significantly increases the affinity of tumor cells to bind to laminin, collagen IV, and collagen I, among other ECM proteins." (PMID 27483328, 2016). "Beyond interactions with HER2 and HER3, MUC4 has been shown to associate with a number of extracellular matrix (ECM) proteins involved in the invasion and metastasis of tumor cells." (PMID 27483328, 2016). "In conclusion, the present study provides evidence that AMOP domain plays the key role in MUC4/Y(MUC4)-mediated tumour angiogenesis and metastasis of PC cells partly through the NOTCH3 signalling and its downstream target genes: VEGF-A, MMP-9 and ANG-2." (PMID 27287498, 2016). "It is identified by using MUC4 staining, which can be helpful to distinguish this tumor type from histologic mimics." (PMID 27247823, 2016). "Conversely, high MUC4 expression of in tumor tissues indicated a higher incidence of NI than low MUC4 expression." (PMID 26393880, 2015). "Immunohistochemical profile of tumor was similar to the first case including strong and diffuse MUC4, vimentin and bcl-2, weak EMA expression except negative immunoreactivity for CD99." (PMID 26449317, 2015). "Then, an immunohistochemical stain for MUC4 was performed which showed strong positivity throughout the tumor." (PMID 26449317, 2015). "We also assessed the effects of MUC4/Y overexpression on tumor vasculature by MVD analysis via CD31 staining of tumors vasculature (the Fourth Line)." (PMID 25367394, 2014). "But only tumor location, tumor differentiation, TNM stage, serum CA19-9, and MUC4 expression were independently associated with survival differences in a multivariate Cox proportional hazards model, which are in accordance with previous reports." (PMID 25367394, 2014). "Coincidentally, bioluminescence imaging revealed that MUC4/Y contributed to enhance the tumor growth rates in the subcutaneous model at the later stages (day26, 30 after injection)." (PMID 25367394, 2014). "We found the MUC4 locus to be the most altered in the tumour tissue compared to that in the control tissue; furthermore, several other mucin genes are also possibly associated to OS." (PMID 25496518, 2014). "Histologic evaluation of the tumors confirmed that MUC4/Y-overexpression markedly increased the fraction of Ki-67-positive tumor cells (the Ki-67 labelling index) compared to the controls (P <0.05, the Second Line)." (PMID 25367394, 2014). "The function predictions and structure analyses of human MUC4 were mostly from the overexpression of its rat homologous gene rMuc4/SMC on human tumor cells." (PMID 25367394, 2014). "The detection of clinical samples indicates that MUC4/Y is significantly positive-correlated with tumor invasion and distant metastases." (PMID 25367394, 2014). "The level of MUC4/Y mRNA expression in PDAC clinical samples indicates that MUC4/Y is significantly positive-correlated with tumor invasion and distant metastases." (PMID 25367394, 2014). "Vein tumor thrombi were obvious in the PANC-1-MUC4/Y group, suggesting that MUC4/Y overexpression aids in PANC-1 cell hematogenous metastasis." (PMID 25367394, 2014). "Western blotting and immunohistochemistry confirmed the upregulation of MUC1 and MUC4 in resistant cells and their corresponding tumor xenografts at the protein levels respectively." (PMID 25327561, 2014). "This pattern differs from the expression patterns involving MUC1, MUC2 or MUC4 that are related to a poor prognosis in neoplasms of other organs." (PMID 24722639, 2014). "Choudhury and colleagues observed that PDAC with high MUC4 expression showed a significant relevance to metastases of distant lymph nodes and faster tumor growth compared to those with MUC4 low expression in vivo." (PMID 24587996, 2014).
tumor (continued). "MUC1 and MUC4 stained the apical portion of glandular tumor cells and the membrane of intermediate and epidermoid tumor cells while MUC2 and MUC5AC stained the cytoplasm of glandular, mucous, and intermediate tumor cells." (PMID 24367734, 2013). "Further the studies on Muc4 shows that it influences tumor growth via the suppression of apoptosis and potentiate metastasis via multiple mechanisms." (PMID 22537161, 2012). "Reduction of ErbB2 expression previously shown in vitro by Western blotting was also confirmed in vivo in MUC4-KD tumours by IHC." (PMID 22393391, 2012). "Mucins are membrane proteins largely investigated as tumor markers, and particularly MUC1 and MUC4 have been implicated in pancreatic carcinogenesis." (PMID 22458520, 2012). "MUC4 is aberrantly expressed in pancreatic adenocarcinoma and tumor cell lines, while remaining undetectable in the normal pancreas or chronic pancreatitis." (PMID 22537161, 2012). "After about 2 weeks, luminescence signals were very high in the “MUC4” injected mice, suggesting efficient gene transfer in the tumor cells (p = 0.018 with a 2-sided Mann Whitney test against control signal, n = 4-5)." (PMID 23088623, 2012). "Most studies using 8G7, which was generated against human MUC4, MUC4/8G7 expression is related to aggressive tumor behavior or a poor outcome in human carcinomas." (PMID 23152882, 2012). "Our study proves that MUC4 is not only expressed on mature cancer cells, but also on tumor cells that have multiple characteristics of stem/progenitor cells." (PMID 21521521, 2011). "MAbs 2214, 2175 and 2382 showed positive staining in the tumor tissue that was determined to be MUC4 positive based on its reactivity with anti-TR MAb 8G7." (PMID 21886786, 2011). "The circular colonies or tumor spheres from MUC4-transfected SKOV3 cells were isolated and grown in a separate glass cover slip for the cancer stem cell marker analysis by confocal microscopy." (PMID 21521521, 2011). "Altered expression of mucins such as MUC1 and MUC4 has been shown to regulate various processes such as tumour cell growth, cell adhesion, motility and tumorigenicity." (PMID 21326240, 2011). "Additional PEA3 family target genes implicated in neoplasia include; urokinase plasminogen activator (uPA), vimentin, cyclooxygenase-2 (COX-2), Twist, MUC4, WT1, osteopontin, mammaglobin, cyclin D3 and HER2." (PMID 20107508, 2010). "Another significant challenge in discerning MUC4 involvement in the progression of many tumor types concerns its detection." (PMID 19761616, 2009). "Collectively, these observations raise the possibility that dysregulation of MUC4 in patient tumors can confer properties to tumor cells that promote tumor progression." (PMID 19761616, 2009). "MUC4 expression levels in patient-matched normal and tumor breast tissue was initially examined by immunoblotting lysates of fresh frozen tissue samples with a highly specific preparation of anti-MUC4 monoclonal antibody 1G8." (PMID 19761616, 2009). "In general, there was very good agreement in average MUC4 staining intensity of normal, primary tumor, and metastatic tissue between the two groups." (PMID 19761616, 2009). "Early studies employed in situ hybridization methods to detect the MUC4 message in normal and tumor tissue." (PMID 19761616, 2009). "In the present study, MUC1 and MUC4 expression identified a subgroup of patients that had a particularly poor prognosis among patients with a differentiated pancreatobility tumour." (PMID 19236510, 2009). "MUC4-positive tumor emboli were often found in lymphovascular spaces of lymph node metastatic lesions." (PMID 19761616, 2009). "In human mammary epithelial cells, MUC4 has an antiadhesive effect and appears to promote tumour growth and progression." (PMID 18475301, 2008). "Similar results were obtained for the tumour volume for Panc1 cells expressing mini-MUC4 vs Panc1 parental (P<0.01) and for Panc1 transfected with mini-MUC4 vs vector-transfected cells (P<0.01)." (PMID 17595659, 2007).
tumor (continued). "Among animals with tumour present, the tumour weight was significantly higher for the Panc1 cells expressing mini-MUC4 as compared with the parental cells (P<0.01) and the vector-transfected cells (P<0.01)." (PMID 17595659, 2007). "Seventy-five percent and 64% of the mice injected with the Panc1 parental or vector-transfected control cells, respectively, developed primary tumours as compared with 100% for the cells expressing mini-MUC4." (PMID 17595659, 2007). "The membrane-associated mucins rat Muc4 and MUC1 have been reported to play a role in tumour progression and metastasis." (PMID 14760381, 2004). "We further analysed the status of MUC4 transcripts in the tumours that are generated in two different host environments." (PMID 14760381, 2004). "To answer the question if there was a clonal expansion of non-MUC4-expressing cells in the SC tumours (showing undetectable levels of MUC4), we isolated and cultured cells from the SC tumours, and studied the MUC4 expression." (PMID 14760381, 2004). "These splice forms, called MUC1/Y, MUC1/X, MUC1/Z, MUC4/X, and MUC4/Y, present a growth factor-like architecture and are thought to be involved in fetal and tumour development." (PMID 15494719, 2004). "The in vitro culture of SC tumour cells returned the expression of MUC4 transcripts to the parental cell line level, further suggesting a role of serum factor(s) in regulating MUC4 expression." (PMID 14760381, 2004). "OT tumours showed an MUC4 transcript similar or little higher than the parental cell line CD18/HPAF." (PMID 14760381, 2004). "The MUC4 transcripts in OT tumours were very high compared to the undetectable levels in SC tumours." (PMID 14760381, 2004). "Overexpression of SMC (rat Muc4) has been shown to promote tumour growth in primary tumours and has resulted in metastasis." (PMID 14760381, 2004). "OT tumour cells in culture showed a transient decrease in the level of MUC4 transcripts and also exhibited a level comparable to MUC4 in CD18/HPAF in the later passages." (PMID 14760381, 2004). "The expression of MUC4 was high in moderately differentiated tumours, with undetectable levels in poorly differentiated SC tumours." (PMID 14760381, 2004). "We studied the tumour histology of the MUC4-expressing OT as well as the tumours showing undetectable MUC4 expression, and were interested to see if there is any correlation with the tumour morphology." (PMID 14760381, 2004). "The morphologically differentiated invasive OT tumours demonstrated a high level of expression of MUC4 mRNA and protein compared to undetectable levels in poorly differentiated SC tumours." (PMID 14760381, 2004). "The MUC4 protein expressions in OT and SC tumour sections were determined by IHC, using a rabbit polyclonal antiserum raised against MUC4." (PMID 14760381, 2004). "When tumours were generated at other MUC4-expressing sites in nude mice like SMG and stomach, these tumours also showed equivalent levels of MUC4 (unpublished result)." (PMID 14760381, 2004). "The SC tumour cells, when cultured in vitro, showed MUC4 expression, suggesting a role of serum factor(s) in its regulation." (PMID 14760381, 2004). "MUC4 overexpression confers tumor cells to apoptotic resistance." (PMID 41296384, 2025). "MUC4, characterized by its extensive glycosylated extracellular region, has the ability to conceal immunogenic antigens on the cell surface, thus shielding tumor cells from immune system recognition." (PMID 40655139, 2025). "Tumors with high MUC4 expression may show altered infiltration patterns of immune cells such as T cells and macrophages, which can contribute to a pro-tumor microenvironment." (PMID 40655139, 2025). "This commercially available (Rockland Immunochemicals) mAb was shown to specifically stain PDAC tissue, bind tumor cells expressing aberrant MUC4, and maintain its specificity against a panel of many TFag-containing molecules on much larger glycan microarrays with a much broader range of components." (PMID 40649822, 2025).
tumor (continued). "However, sustained TNF-α signaling in the tumor microenvironment has been shown to induce MUC4 expression, which masks the HER2 epitope and reduces trastuzumab efficacy, thereby facilitating immune evasion." (PMID 41400702, 2025). "In addition, MUC4 enhances tumor cell migration and invasion by suppressing the expression of the intercellular adhesion molecule and the integrin receptor." (PMID 40655139, 2025). "The reticular structure formed by the secreted mucus, as well as the extraordinary size of heavily O-glycosylated membrane-bound mucins such as MUC1 or MUC4, are capable of limiting drug intracellular entrance and immune recognition of tumor cell epitopes in antibody-based therapies." (PMID 38380362, 2024). "MUC4 expression triggers neoplastic transformation, enhances both tumorigenesis and metastasis, and influences the interaction and communication between components of the tumor microenvironment and cancer cells." (PMID 39458160, 2024). "Additionally, several studies demonstrated that upregulated MUC1 and MUC4 expression plays an important role in tumor cell metabolism, mesenchymal transition, apoptosis, and metastasis (Qing, Li & Dong, 2022)." (PMID 38274327, 2024). "In addition, studies have shown that MUC4 can interact with key tumor-related signaling pathways to promote tumor cells proliferation, invasion, metastasis, and chemoresistance in pancreatic cancer." (PMID 38816411, 2024). "Additionally, the aberrant glycosylation within and around MUC-4 has shown to contribute to tumor growth." (PMID 38776309, 2024). "MUC4-/- mice showed an attenuated colitic response to dextran sodium sulphate and a reduced tumour burden compared to wild-type mice suggesting a role for MUC4 in inflammation and progression to neoplasia, however, the discrepancy between studies implies it is a complex relationship." (PMID 38505585, 2024). "Recently, it was demonstrated that Muc4 may facilitate tumor cell survival in circulation and, therefore, metastasis by promoting the association of circulating tumor cells with blood cells." (PMID 37367035, 2023). "MUC4 may act as an intramembrane ligand for the receptor tyrosine kinase ErbB2 and perform an anti-apoptotic function to promote tumor progression." (PMID 37384668, 2023). "In these tumor samples, the top 10 mutated genes included PIK3CA, MUC4, and TTN." (PMID 35528180, 2022). "The mucus-producing marker MUC4 was positive in both tumor tissue and tumor organoids." (PMID 36527158, 2022). "Since MUC4 builds up slowly while the tumor progresses, we can speculate that in advanced tumors it plays a role in intrinsic resistance." (PMID 35626089, 2022). "Western blot studies demonstrated the increased MUC4 expression in 87MUC4 cells and tumor tissues." (PMID 35910795, 2022). "MUC4 facilitates metastases by promoting a group of tumor cells that diffuse into the bloodstream." (PMID 34635181, 2021). "The MUC4 expression profile observed in KIRC and TGCT may suggest a link between the level of MUC4 and the tumor stage." (PMID 34336844, 2021). "We wondered whether MUC4 was differentially methylated between tumor and normal samples, and we used UALCAN to compare their methylation level in dependent cancer types." (PMID 34336844, 2021). "Additionally, MUC4 has been shown to reduce the interactions between cells, promote cell separation, and promote tumor metastasis." (PMID 33718192, 2021). "Furthermore, MUC4 confers antiadhesive properties to tumor cells allowing their systemic dissemination." (PMID 32391269, 2020). "During cancer progression, galectin‐3‐MUC4 interaction–mediated clustering of MUC4 may expose the surface adhesion molecules, which in turn promotes a stronger attachment (locking) of tumour cells to the endothelial surface." (PMID 32886424, 2020).
tumor (continued). "Among the best-known membrane-bound mucins, MUC1 and MUC4 have been extensively proposed as drivers of pancreatic carcinogenesis because they promote tumor growth, proliferation, oncogenic signaling, cell metabolism, epithelial–mesenchymal transition (EMT), and metastasis." (PMID 33182511, 2020). "Essentially all (~100%) of the neoplastic cells in these endothelial lined structures are positive for MUC4, suggesting that the antiserum bound a higher percentage of aggressive tumor cells displaying vascular invasion than the more heterogenous staining observed in the primary tumor." (PMID 30952968, 2019). "We have found that TQ-induced TTP might inhibit metastasis by reducing tumor cell migration and invasion through destabilization of MUC4 mRNA, which suggest the MUC4 as a novel target to TTP." (PMID 31141941, 2019). "Of the neoplasms evaluated, significantly increased MUC4 expression was observed in histologically high-grade tumors (grade 3); thus, assays to determine MUC4 expression may be a useful prognostic indicator." (PMID 30952968, 2019). "Through its epidermal growth factor (EGF) domains, MUC4 may act as an intramembrane ligand for receptor tyrosine kinase ErbB2 and execute antiapoptotic function and by that promote tumor progression." (PMID 31091244, 2019). "Moreover, interactions between MUC4 glycans and galectin-3 were shown to also mediate docking of circulating tumor cells to the surface of endothelial cells." (PMID 30236127, 2018). "We confirmed MUC4 overexpression in tumor tissues (p < 0.0001)." (PMID 30236127, 2018). "Moreover, taurine deoxycholic acid can significantly up-regulate the expression of MUC4 (a membrane-bound mucin) by activating phosphatidylinositol 3-kinase, thereby affecting cell proliferation and tumor progression." (PMID 30555525, 2018). "For example, MUC4 is proposed to contribute to tumor progression by promoting cell survival." (PMID 29023534, 2017). "MUC4 has been correlated with progression and higher tumor grade." (PMID 28915583, 2017). "However, the role or effect of the three unique domains on MUC4-mediated functions and mechanisms is unclear, especially when in different tumor microenvironment." (PMID 28060749, 2017). "A nearly significant (p = 0.0795) in-frame mutation at 4045 is associated with increased aggressive behavior of the tumor, while all other mutations appeared to have improved survival compared to patients without MUC4 mutations in KIRC stage I patients." (PMID 28978023, 2017). "Furthermore, association of MUC4 and HER2 results in stabilization of the complex and can protect tumor cells from trastuzumab, a targeted therapy against HER2." (PMID 27483328, 2016). "Additionally, the NIDO domain of MUC4 has also been shown to play a critical role in the migration and invasion of tumor cells." (PMID 27483328, 2016). "In this study, we investigated whether the deletion of the AMOP domain could alter MUC4(MUC4/Y)-mediated tumour biological processes in PC cells." (PMID 27287498, 2016). "Among them, MUC4, first identified as a tracheobronchial mucin in 1991, has been demonstrated to be with various functional roles in tumor progression and metastasis, and thus may serve as a potential predictor of tumor prognosis." (PMID 27305093, 2016). "In addition, as reported, the presence of MUC4 on tumor cell would cloak the surface epitopes to the cytotoxic immune cells, which helped the tumor cells escape from immunological attack." (PMID 27305093, 2016). "We found that the deletion of AMOP domain could reverse the tumour angiogenesis and metastasis induced by MUC4/Y." (PMID 27287498, 2016). "Moreover, miRNA-219-1-3p injection in xenografted pancreatic tumors in mice decreased both tumor growth and MUC4 mucin expression." (PMID 26259238, 2015).